STAT3 (signal transducer and activator of transcription 3)
Diseases named in the same sentence as STAT3 in open-access papers (continued):
Sharing a sentence is not in itself a finding about the gene and the disease.
lung carcinoma (continued). "We found that STAT3 expression was not only elevated in lung carcinoma, but also positively correlated with the expression of both miR-4293 and WFDC21P." (PMID 34301920, 2021). "Strong evidence has demonstrated that aberrant STAT3 signaling promotes the initiation and progression of human cancers (including lung cancer) by either inhibiting apoptosis or inducing cell proliferation, angiogenesis, invasion, and metastasis." (PMID 33708630, 2021). "For example, the interplays of long noncoding RNA HOXA11-AS1/miR-454/STAT3 drove chemoresistance of lung cancer." (PMID 34321456, 2021). "W2014-S strongly suppressed proliferation, survival, migration and invasion of lung cancer cells with aberrant STAT3 activation and inhibited the growth of human NSCLC cell xenografts and PDX tumor xenografts in mouse model." (PMID 33391507, 2021). "Using the NSCLC‐derived cell line A549, we examined the expression of Gal‐3 in lung cancer cells under hypoxic conditions and investigated the regulatory effect of Gal‐3 on PD‐L1 expression, which is mediated by the STAT3 pathway." (PMID 33455075, 2021). "Lung cancer cells have been shown to be susceptible to polyI:C combined with inhibitors of IL6 and JAK2/STAT3." (PMID 33562773, 2021). "Our data provide mechanistic insights into the tumorigenic effects of DDIAS, linking NFATc1 function in immune cells to the role of STAT3 in the proliferation and survival of lung cancer cells." (PMID 33859351, 2021). "Subsequently we detected the expression of p-STAT3 and STAT3 in lung cancer patients-derived tissue." (PMID 34059647, 2021). "STAT3 acts as a key regulator of alternatively activated macrophages in pre-clinical models of lung cancer, and also induces surface expression of PDL1 to suppress anti-tumor immune responses." (PMID 34944848, 2021). "Persistent STAT3 activation is associated with tumor progression of head and neck cancer, NPC, prostate cancer, and lung cancer, implying that phosphorylation of STAT3 is a favorable marker of prognosis of various types of cancer." (PMID 34354046, 2021). "Depletion or inhibition of PRMT5 dramatically dampens STAT3 activation and thus suppresses the proliferation of human lung cancer cells." (PMID 34026434, 2021). "Normal STAT3 signaling is tightly controlled in standard cellular response, but constitutive STAT3 activation frequently occurs in a variety of human cancers, especially in lung cancer 25, 29-33." (PMID 33391507, 2021). "Consistently, the cell cycle-and apoptosis-related protein expressions of mTOR, STAT3, Bcl-2, and cyclin D1 significantly increased in A549 lung cancer cells after treatment with 100 ng/ml leptin." (PMID 33708630, 2021). "Deletion of Gprc5a resulted in persistent signal transducer and activator of transcription 3 (Stat3) activation that was important for lung cancer cell survival and transformation." (PMID 33753999, 2021). "Contradictively, a recent study showed that MVP inhibited lung cancer cell proliferation by suppressing the STAT3 pathway." (PMID 35433709, 2021). "For example, PLOD3 can promote lung cancer metastasis by regulating STAT3, and PLOD3 silencing can inhibit the proliferation of glioma cells via P21 pathway." (PMID 34576068, 2021). "On the contrary, hypoxic BMSC-derived exosomal miRs (including miR-5100) promote metastasis of lung cancer cells via STAT3-induced EMT." (PMID 34868998, 2021). "Curcumin was found through the JAK2/STAT3 pathway to reduce tumorsphere growth in H460 lung cancer cells in in vivo and in vitro studies." (PMID 34209829, 2021). "Collectively, our findings illustrate that PRMT5 contributes to human lung cancer cell proliferation and migration via modulating STAT3 signaling." (PMID 34026434, 2021). "The findings position PRMT5 as a critical regulator of STAT3 activation, and suggest it as a potential therapeutic target for the treatment of human lung cancer." (PMID 34026434, 2021).
lung carcinoma (continued). "Our results also indicated that the drug resistance of lung cancer cells was achieved through activating the STAT3/VEGF signaling pathway, which was consistent with previous research." (PMID 34129726, 2021). "Perhaps more importantly, silibinin-driven STAT3 blockade holds immense promise in areas of highly unmet clinical need such as lung cancer brain metastasis, which portend a poor prognosis and have very few therapeutic options." (PMID 34208282, 2021). "In conclusion, we found that Rab37-mediated exocytosis of IL-6 from macrophages promotes PD-1 upregulation in T cells via the Rab37/IL-6/STAT3 transcription axis to support lung cancer progression." (PMID 34093869, 2021). "Jing Li reported that phosphorylation of PKM2 and inactivation of STAT3 inhibited lung cancer cell proliferation." (PMID 34285141, 2021). "Inactivation of STAT3 is a target for increasing cisplatin sensitivity in lung cancer treatment, galangin, and laricitrin are STAT3 inhibitors in adjuvant chemotherapy." (PMID 34512360, 2021). "STAT3-targeted inhibition therefore is a new potential therapeutic strategy for gefitinib resistance in lung cancer." (PMID 34059647, 2021). "The results demonstrated that the expression of p-STAT3 is significantly increased in lung cancer tumor, especially in resistance tumor tissues." (PMID 34059647, 2021). "In lung cancer, plasma exosomes secreted by hypoxemic BMSCs can promote the invasion of lung cancer cells by activating the STAT3 signalling and EMT." (PMID 33722297, 2021). "LL1, a novel STAT3 inhibitor significantly sensitize lung cancer cells to gefitinib in vitro and in vivo." (PMID 34059647, 2021). "Depletion or inhibition of PRMT5 dramatically dampens STAT3 activation and suppresses proliferation and migration of human lung cancer cells." (PMID 34026434, 2021). "We show that Ang II–mediated activation of the AT1-R promotes cell proliferation and anchorage-independent growth of lung cancer cells through a STAT3-dependent pathway." (PMID 33380422, 2021). "W2014-S strongly suppressed proliferation, survival, migration and invasion of lung cancer cells with aberrantly-active STAT3, and induced cell apoptosis." (PMID 33391507, 2021). "Our data also identified PDLIM2 downregulation in AMs and monocytes by ROS-activated BACH1 to increase STAT3 activation as a mechanism driving these immune cells to promote lung cancer." (PMID 33539325, 2021). "Wang et.al reported that HHT induced apoptosis and inhibited STAT3 via IL-6-JAK1-STAT3 signaling pathway in lung cancer cells." (PMID 33867824, 2021). "Consistent with previous reports demonstrating a role for STAT3 in mediating the epithelial-to-mesenchymal transition (EMT) of lung cancer cells, inhibition of STAT3 by cucurbitacin I also inhibits the migratory and metastatic ability of CD133+ CSCs in vivo." (PMID 34944848, 2021). "It is reported that STAT3 signaling pathway participates in regulation of SIN against lung cancer and osteosarcoma cells." (PMID 34179090, 2021). "CCL2 (or monocyte chemotactic protein 1 (MCP1)) displays overexpression in TAM and triggers EMT in lung cancer with IL-6 through activation of Twist/STAT3." (PMID 34220337, 2021). "Leptin can upregulate GRP78 expression through the PI3K/TOR/STAT3 signaling pathway in neuronal and lung cancer cells." (PMID 33708630, 2021). "Combination of STAT3 inhibitor with gefitinib is more effective to inhibit TKI-resistant lung cancer xenograft growth than single treatment." (PMID 33391507, 2021). "A different study revealed that FZKA induced lung cancer cell apoptosis involving the STAT3/BCL-2/Caspase-3 pathway." (PMID 33585660, 2021). "STAT3 activation in B-cells enhances tumor angiogenesis via upregulation of VEGF in lung cancer allografts and increases surface expression of immune checkpoint molecules such as CTLA4." (PMID 34944848, 2021).
lung carcinoma (continued). "To further validate and expand these studies, we tried to define the mechanism by which PDLIM2/STAT3 signaling controls the pulmonary recruitment of blood monocytes, the prerequisite for AM expansion and lung cancer promotion." (PMID 33539325, 2021). "In lung cancer, STAT3 was shown to play an unexpected tumor-suppressive role in KRAS-mutant lung adenocarcinoma." (PMID 34679602, 2021). "As upstream mediator, aryl hydrocarbon receptor induces JAK2/STAT3 axis to promote lung cancer stemness." (PMID 34769099, 2021). "Some lncRNAs function as ceRNAs to competitively bind shared sequences of miRNAs and regulate mRNA generation and function, which has been reported to participate in cell proliferation via inactivating the STAT3 signaling pathway in lung cancer 43,44,49,78,87." (PMID 33628581, 2021). "Persistently activated or tyrosine-phosphorylated Stat3 (p-Stat3) is found in 54% of NSCLC primary tumors, suggesting that Stat3 is a promising molecular target for lung cancer." (PMID 33959611, 2021). "Consistent with the data obtained in lung cancer cells, the level of phospho(Tyr705)-STAT3 in the lungs of K-RasLA2-G12D mice was downregulated by the treatment with losartan." (PMID 33380422, 2021). "The currently available literature indicates that exosomal miR-210 is involved in the regulation of various lung cancer-related signaling molecules and pathways, including STAT3, TIMP-1, KRAS/BACH2/GATA-3/RIP3, and PI3K/AKT." (PMID 34440422, 2021). "Through analyzing the TCGA database via the Gene Expression Profiling Interactive Analysis (GEPIA), we found that the expression of STAT3 were correlated with ZEB1 in both lung cancer tissues and normal tissues." (PMID 34059647, 2021). "For the first time, we found that the PI3K/Akt/mTOR/STAT3 pathway was also involved in the effect of leptin on lung cancer cell growth." (PMID 33708630, 2021). "It is demonstrated that circHIPK3 can restore lung cancer cell survival and proliferation via sponging miR-124 and regulating expression of its potential targets such as SphK1, STAT3, and CDK4." (PMID 33634138, 2021). "In pre-clinical models of lung cancer, STAT3 promotes MDSC development and proliferation, and induces the expression of key pro-apoptotic mediators to kill cytotoxic T-cells." (PMID 34944848, 2021). "It has been reported that silencing of ERβ promotes the invasion and migration of osteosarcoma cells via activating Wnt signaling pathway and the activation of STAT3 signaling up-regulates ERβ expression in lung cancer cells." (PMID 34922636, 2021). "We recently combined experimental, computational, and clinical efforts to investigate how silibinin imparts therapeutic benefits to patients with lung cancer by targeting STAT3." (PMID 34208282, 2021). "We found that IFNγ simultaneously increased phosphorylation on STAT1 and STAT3 in EGFR-positive lung cancer, resulting in overexpression of PD-L1 (p < 0.05)." (PMID 34685495, 2021). "In tumor studies with HCC, lung carcinoma, and melanoma, it was also shown that inhibition of Stat3 in macrophages abrogated their M2 polarization and protumorigenic effects." (PMID 33749663, 2021). "Activation of STAT3 signaling in glioma and lung cancer has been suggested to be involved in the resistance to gefitinib." (PMID 33392396, 2021). "Regulatory B-cells that express high levels of STAT3 have also been identified in the draining lymph nodes of lung cancer patients and promote tumor progression by inducing angiogenesis and immunosuppression via production of IL10." (PMID 34944848, 2021). "CAFs isolated from human lung cancer tissue secrete IL-6, which stimulates JAK2 and STAT3 signal transduction in human lung cancer cells, thereby increasing metastasis." (PMID 34079469, 2021). "This study showed that the increased expression of Gal‐3 was induced by hypoxia, which then contributed to immune suppression through the STAT3 pathway in lung cancer." (PMID 33455075, 2021).
lung carcinoma (continued). "Central to the tumor cell-intrinsic and microenvironmental effects of silibinin in lung cancer is the transcriptional factor STAT3." (PMID 34208282, 2021). "A recent study provided evidence that silencing circHIPK3 induced lung cancer cell death and apoptosis, by sponging miR-124 and regulating miR-124 targets, including SphK1, STAT3 and CDK4 proteins." (PMID 34295810, 2021). "In the present study, we report that Gal‐3 promoted PD‐L1 expression in lung cancer cells via the STAT3 pathway." (PMID 33455075, 2021). "To explore the role of the miR-526b-3p/STAT3 axis in the regulation of lung cancer malignancy, we introduced miR-526b-3p and STAT3 into cells." (PMID 34321456, 2021). "A previous study has shown that STAT3 is involved in fraxetin-mediated inhibition in the proliferation of lung cancer cells." (PMID 34320467, 2021). "We observed that Hiltonol+++ (Hiltonol in combination with inhibitors of IL6, JAK2, STAT3) significantly suppressed the viability of lung cancer cells compared to Hiltonol alone." (PMID 33562773, 2021). "In osteosarcoma cells, curcumin inhibited the p-JAK2/p-STAT3 pathway which was involved in lung metastasis whereas in lung cancer, curcumin suppressed activation of p-STAT3 both in vitro and in vivo." (PMID 34867402, 2021). "A similar mutation was observed for FGFR1 (FGFR1-V561M) in lung cancer, which drives resistance to AZD4547 through the activation of STAT3 and EMT." (PMID 34830951, 2021). "Alternatively, EV-derived miR-210 and miR-155-5p induce a pro-angiogenic switch in CAFs through the activation of the JAK-2/STAT-3 pathway in lung cancer and melanoma." (PMID 33553157, 2020). "We expect multiple, intertwined crosstalks and interactions between DDIAS/PTPRM and other STAT3 regulation system in lung cancer cells." (PMID 31900385, 2020). "In conclusion, CHK9 exhibits growth-inhibitory potential by abrogating STAT3 signaling in lung cancer cells." (PMID 32967366, 2020). "Reports have indicated that miR-296-5p acts as a tumor suppressor in lung cancer and that STAT3 can contribute to cisplatin resistance." (PMID 32799866, 2020). "We observed that A009 extracts, 1:250 dilution, batch 4 and 3 can reduce the phosphorylation of STAT3 (Tyr705) on A549 and H1650 lung cancer cells." (PMID 32224910, 2020). "We further plan to screen drugs inhibiting the interaction between DDIAS and STAT3 and investigate the effectiveness of this drug in combination with the currently available treatment for lung cancer." (PMID 31900385, 2020). "Cucurbitacin I was also able to induce pro-death autophagy signalling in lung carcinoma cells through ERK/mTOR/STAT3 signalling by inhibiting ERK activation and the downstream phosphorylation of mTOR and STAT3." (PMID 32731620, 2020). "FUZ is a critical regulator of cilia structure, whose expression is associated with poor prognosis in lung cancer patients; this effect of FUZ is mediated through the activation of ERK1/2 and JAK2/STAT3 signaling via the formation of the FUZ–BNIP3 complex." (PMID 31952344, 2020). "Our previous studies demonstrated that bee venom and melittin inhibited the STAT3 pathway and induced the cell growth inhibition of lung cancer." (PMID 31929760, 2020). "For example, exosomes derived from hypoxic bone mesenchymal stem cells (BMSCs) transferred miR‐193a‐3p, miR‐210‐3p and miR‐5100 to lung cancer cells and activated STAT3 signalling‐induced EMT, promoting metastasis." (PMID 32391938, 2020). "STAT3 is constitutively activated and often required to maintain the transformed phenotype in a majority of malignant tumors including lung cancer, functioning as an oncogene." (PMID 33318313, 2020). "In conclusion, our results suggested dioscin elicits anti‐tumour immunity by inhibiting macrophage M2 polarization through JNK and STAT3 pathways in lung cancer." (PMID 32618105, 2020). "A study demonstrated that STAT3 and NF-κB signaling pathways were simultaneously attenuated in dendritic cells of lung cancer." (PMID 33014809, 2020).
lung carcinoma (continued). "The role of STAT3 signaling in immune cells and its effects on tumor-promoting inflammation and anti-tumor immunity was also addressed in lung cancer." (PMID 32365499, 2020). "We further tested if MS3-6 inhibits STAT3 transcriptional activity in A549 lung cancer cells, which endogenously express the hIL-6 and hIL-22 receptors." (PMID 32807795, 2020). "The signal transducer and activator of transcription 3 (STAT3) has been shown to be involved in the enhancement effect of lung cancer cells’ sensitivity to doxorubicin by berberine." (PMID 32245062, 2020). "Uncontrolled STAT3 phosphorylation can lead to uncontrolled cell proliferation and malignant transformation, and thus promote the occurrence of lung cancer." (PMID 33299414, 2020). "In lung cancer, IL-6/STAT3 signalling induced by KRAS oncogene has contrasting roles in its initiation and progression." (PMID 33116132, 2020). "We newly identified the DDIAS/PTPRM/STAT3 system in lung cancer cells with aberrant STAT3 expression." (PMID 31900385, 2020). "The doxorubicin-mediated STAT3 activation was also inhibited by berberine leading to a greater sensitivity of lung cancer cells to apoptosis induction by doxorubicin." (PMID 32245062, 2020). "In vitro and in vivo studies showed that the CHK9 exhibits the anticancer activity by inhibiting STAT3 signaling in lung cancer cells." (PMID 32967366, 2020). "EGFR‐activated STAT3, for example, is critical for lung cancer metastasis (Soon, Leong, Koh, & Tham, 2015)." (PMID 33304472, 2020). "Our findings suggest a novel pathway for DDIAS-mediated aberrant activation of STAT3 in malignant lung cancer cells." (PMID 31900385, 2020). "STAT3 is an oncogenic transcription factor that is persistently activated in many types of human malignancies, including lung cancer." (PMID 32967366, 2020). "E2F1 and STAT3 have been reported to promote the transcription of Linc00668, respectively, in gastric cancer and in lung cancer." (PMID 32117742, 2020). "Further, lung epithelium-specific deletion of STAT3 increased NK cell immunity, thereby impairing tumor growth in a carcinogen-induced lung cancer mouse model." (PMID 32365499, 2020). "We examined the subcellular localization of endogenous STAT3 and HP1α in in serum starved cells using several lines of lung cancer cells including A549, H226, H441, H460, H520, as well as HeLa and HEK293T cells." (PMID 32087696, 2020). "For example, it has been reported that PGE2 mediates Src kinase activation and STAT3 phosphorylation in lung cancer." (PMID 32171274, 2020). "In this study, we demonstrated that DDIAS promoted IL-6–mediated STAT3 activation in lung cancer cells by competing with PTPRM." (PMID 31900385, 2020). "In summary, we provide novel insights into the crucial role of DDIAS in STAT3 signaling in malignant lung cancer." (PMID 31900385, 2020). "STAT3 has been intensively studied as a therapeutic target for cancer of pyrimethamine including lung cancer." (PMID 32549310, 2020). "On the other hand, IL-6, produced by cancer-associated fibroblasts (CAFs), induces invasion, metastasis, and EMT properties in lung cancer via STAT3 pathway." (PMID 33352869, 2020). "It is well known that Stat3 is constitutively activated in numerous cancer types, and metformin suppresses the Stat3 activation in lung cancer and ESCC cells." (PMID 32258099, 2020). "High expression of MALAT1 decreased cisplatin sensitivity in lung cancer, and the mechanism is associated with upregulated Multidrug resistance-associated protein 1 (MRP1) and Multi-Drug resistance 1 (MDR1) via STAT3." (PMID 32708561, 2020). "In line with the role of IL6 in lung tumor, the signal transducers and activators of transcription 3 (STAT3), the well defined downstream effector of IL-6, also prevents lung cancer initiation." (PMID 32134471, 2020). "Herein we synthesized new derivatives of oxadiazole and indazole conjugates and tested them for possible anticancer and STAT3 inhibitory potential in lung cancer cells." (PMID 32967366, 2020).